RNU6-1256P (RNA, U6 small nuclear 1256, pseudogene)
Gene: Small nuclear RNA gene on chromosome 3 (101,615,826 to 101,615,928, forward strand). Ensembl gene ENSG00000252348.
Homologues: Orthologues: chimpanzee U6 (99% identical), macaque U6 (93% identical), rabbit U6 (82% identical), rat U6 (81% identical). Paralogues in human: RNU6-41P (84% identical), RNU6-17P (83% identical), RNU6-18P (83% identical), RNU6-25P (83% identical), RNU6-29P (83% identical), RNU6-35P (83% identical), RNU6-393P (83% identical), RNU6-669P (83% identical), RNU6-1 (83% identical), RNU6-1131P (83% identical), RNU6-1145P (83% identical), RNU6-1152P (83% identical), and 1287 more.